TBK1 (TANK binding kinase 1)
Diseases named in the same sentence as TBK1 in open-access papers (continued):
Sharing a sentence is not in itself a finding about the gene and the disease.
infection (265 papers, 2007 to 2026). The state of being infected such as from the introduction of a foreign agent such as serum, vaccine, antigenic substance or organism. "M3 efficiently inhibited the infection-induced activation of IRF3, which is caused by the phosphorylation of Ser386 in IRF3 by TBK1 in both early and later stages of infection." (PMID 39601535, 2025). "Depletion of TBK1 caused a loss of pSTAT1 in the WT infection and, therefore, the late phase activation of STAT1 is dependent on TBK1 signaling in infection." (PMID 37289831, 2023). "Consistently, we observed that PTK2B deficiency reduced the formation of TBK1 granules induced by HSV1-GFP infection." (PMID 37989995, 2023). "We observed that Ptk2b deficiency reduced the dimer of phosphorylated TBK1 induced by the infection of Sendai virus." (PMID 37989995, 2023). "Other E3 ubiquitin ligases, such as TRAF3 or Mind bomb (MIB), play key roles in K63-linked TBK1 ubiquitination, promoting TBK1 activation shortly after infection." (PMID 37032653, 2023). "As a central mediator of innate immune defense system, TBK1 activates downstream genes for production of type I interferons (IFNs) and other inflammatory cytokines against pathogenic infection." (PMID 37935918, 2023). "Our data indicate that MK2 is upstream to this TBK1-dependent clearance process and that the level of activated TBK1 (pS172-TBK1) was higher in MK2 expressing MEFs after infection in comparison to MK2-deficient MEFs." (PMID 37771590, 2023). "HSV1-GFP infection induced robust Tyr phosphorylation of TBK1 in wild-type RAW 264.7 cells, whereas Ptk2b deficiency reduced this effect." (PMID 37989995, 2023). "Our infection studies in autophagy-deficient KO cells clearly place TBK1 upstream of autophagy activation in the cellular response to Ad infection." (PMID 35857795, 2022). "We conclude that UL138 inhibits innate immune signaling during HCMV productive infection of fibroblasts with a clinical strain virus despite the presence of at least nine additional virally encoded cGAS/STING/TBK1 pathway antagonists." (PMID 34903048, 2021). "We conclude that UL138 inhibits innate immune signaling during HCMV productive infection of fibroblasts with a laboratory strain virus despite the presence of nine additional virally encoded cGAS/STING/TBK1 pathway antagonists." (PMID 34903048, 2021). "We also demonstrated the increased association of OPTN and TBK1 during infection, which was followed by association of OPTN and VP16." (PMID 34518549, 2021). "In response to infection, pattern recognition receptors (PRRs) sense the pathogen-associated molecular patterns (PAMPs) on bacteria or viruses to activate TBK1-mediated signaling pathways." (PMID 33193441, 2020). "Upon infection with different DNA and RNA viruses, TBK1 is K33-linked ubiquitinated, which leads to IRF3 activation." (PMID 32039206, 2019). "York’s group recently identified that STING/TBK1 signalling is critical to the production of type I interferons to reprogram lipid biosynthesis in pathogenic infection." (PMID 28596706, 2017). "Glycan‐ and ubiquitin‐encoded signals can provide functionality to TBK1 for cytosolic defense against invading bacteria at different stages of infection." (PMID 27370208, 2016). "Sendai virus-induced IRF3 and TBK1 phosphorylation were dramatically reduced in MIB1/MIB2 double deficient MEFs compared to control mib1f/f MEFs in early infection." (PMID 23028469, 2012). "Furthermore, we observed that ME49 infection results in increased total ubiquitination and K48‐linked polyubiquitination of TBK1 in BMDMs over a prolonged period, but this tendency was abandoned during ME49Δgra4 infection." (PMID 39031880, 2024). "In contrast with another study, we did find a TBK1-mediated response to HP-PsV infection, albeit modest, which may be caused by differences in cell type or pseudoviral load." (PMID 38485766, 2024).
infection (continued). "In humans, IRF3 and TBK1-deficient patients have been reported to have increased susceptibility to herpes-induced encephalitis (HSE) as well as an increase in reoccurrence of infection." (PMID 36680267, 2023). "Here, we show that the latency-associated protein UL138 inhibits the cGAS/STING/TBK1 innate immunity pathway during transfections and infections, in fully differentiated cells and incompletely differentiated myeloid cells, and with loss of function and restoration of function approaches." (PMID 34903048, 2021). "Transfection of miR-15b mimics could almost abolish upregulation of TBK1 expression caused by SCRV infection in MKC cells." (PMID 33584728, 2020). "TBK1 mutations causing autosomal dominant TBK1 deficiency have been identified in HSE patients resulting in impaired IFN production leading to enhanced cell death upon infection with HSV-1." (PMID 30794036, 2019). "More work is required to clarify how those unknown TBK1 spliced isoforms regulate each other during pathogenic infection." (PMID 29441066, 2018). "Ubiquitination of TBK1 seemed an efficient tactic to activate IFN response because the endogenous TBK1 was K63-linked poly-ubiquitinated at 8 h post Sendai virus (SeV) infection and accompanied with phosphorylation of IRF3 and STAT1, the indications of the IFN production." (PMID 21364999, 2011). "Intriguing enough, although overexpressed IRF3 could recruit TBK1 (top panel lane 2), infection with MHV-A59 led to enhanced association of endogenous TBK1 with the complex (top panel lane 4)." (PMID 21364999, 2011). "Hence, TBK1 kinase could mirror PINK1 activity during infection; however, further investigation of the functional association between TBK1 and Parkin is needed." (PMID 29951054, 2018). "During SVCV infection, cells overexpressing TBK1 showed little CPE; however, CDK2 dramatically counteracted the antiviral capacity of TBK1, as confirmed by virus titer identification." (PMID 41532831, 2026). "In B cells, TBK1-specific knockout rendered memory B cells unable to achieve aseptic immunity upon re-infection, impairing humoral immunity and resulting in the development of human IgA nephropathy-like disease in mice." (PMID 40076567, 2025). "Deletion of the LIT domain from ALTO not only abolishes TBK1 interaction and downstream phosphorylation but also eliminates TBK1-mediated suppression of MCPyV replication during early infection of human dermal fibroblasts." (PMID 41277846, 2025). "After the knockdown of TBK1 in B cells, the generated memory B cells fail to achieve aseptic immunity upon re-infection, suggesting that TBK1 determines the fate of B cells in promoting durable humoral immunity." (PMID 40076567, 2025). "This confirmed that the induction of IFN mRNAs early in infection through TBK1 and IRF3 activation is essential for virus propagation." (PMID 39601535, 2025). "After infection, both cell types showed an increment of the total protein levels of NF-κB and TBK1 in infected cells." (PMID 41139159, 2025). "Following infection, viral RNA is recognized by RLRs and TLRs, leading to modifications by downstream signaling proteins such as Visa, Tbk1, and Myd88." (PMID 40547011, 2025). "In similar experiments, the induction of IFNB1 mRNA and the phosphorylation of TBK1 following infection with another DNA virus, HSV-1 (F-strain), were significantly increased." (PMID 40237449, 2025). "HSV1 infection led to rapid suppression of phospho-STING and subsequent reduction of phospho-TANK-binding kinase 1 (TBK1) at 8 hours post infection (hpi)." (PMID 40303347, 2025). "Upon SVCV infection, zebrafish mylipb-C381S interfered with the antiviral function of tbk1 in terms of both CPE and viral titer." (PMID 38739631, 2024). "As such, LUBAC is specifically and transiently recruited to NEMO and TBK1 in an SeV-infection-dependent manner, consistent with the requirement for HOIP protein and E3 ligase activity in RIG-I signalling." (PMID 38001254, 2024).
infection (continued). "Our findings indicate that TBK1 is targeted during late stages of infection, and there are several potential reasons for this observation." (PMID 38400023, 2024). "SARS-CoV-2-infected Calu-3 cells demonstrated decreased levels of TBK1 and p62 at 8 h post infection." (PMID 39339967, 2024). "The levels of p62 and TBK1 in the infected cells decreased at 8 h post infection as a time-dependent variable." (PMID 39339967, 2024). "High MOI infection in the IPEC-J2 cells demonstrated that TBK1 levels were reduced, in agreement with our previous observations." (PMID 38400023, 2024). "To further unveil the function of CPSF6 in virus-triggered innate immune responses, we measured the levels of phosphorylated IRF3 and TBK1 and observed that CPSF6 deficiency markedly facilitated TBK1 and IRF3 phosphorylation after VSV-eGFP infection." (PMID 38416782, 2024). "We observed that IRF-3 and TBK1 levels were significantly elevated in the Berb-treated group compared to the infection group." (PMID 39640591, 2024). "To determine if the increased IFN response in OPTN KO cells during infection depends on TBK1 expression, we silenced TBK1 in OPTN KO cells." (PMID 38019030, 2023). "On the other hand, mice treated with a TBK1 inhibitor died approximately 4 days earlier than untreated mice after EV-A71 infection, suggesting that TBK1 inhibitor contributed to EV-A71 pathogenesis." (PMID 36626364, 2023). "We show that in conditions of TBK1 deficiency, IKKε induction is crucial to ensure unmitigated type I IFN responses after specific activation of cGAS and RLRs, and also during infection with Listeria monocytogenes." (PMID 36936901, 2023). "Precise insights into OPTN’s interactions with TBK1 during infection, both in its presence and absence, remain elusive." (PMID 38019030, 2023). "Altogether, these findings indicate that therapeutic inhibition of TBK1/IKKε as late as 3 days post-infection is superior to that of direct STING inhibition for protection against SARS-CoV-2-driven lung hyper-inflammation." (PMID 37723181, 2023). "Our results are consistent with that of the Kalejta laboratory in that changes in innate signaling in infection appear to occur independently of changes in total or phosphorylated levels of TBK1 and STING." (PMID 37289831, 2023). "In the presence of VitD and rxrbb during GCRV infection, the double knockout of grass carp vdra and vdrb significantly induced the transcriptions of mda5, rig-I, mavs, tbk1, irf3, irf7, and mx1." (PMID 37466438, 2023). "Overall, these data demonstrate that in conditions of TBK1 deficiency, IKKε upregulation is crucial to ensure efficient type I IFN production during infection." (PMID 36936901, 2023). "TANK-binding kinase-1 (TBK1) and its homologue IκB kinase-ε (IKKε) are critical in the induction of the interferon response and the response to infection by pathogens." (PMID 37723181, 2023). "Further studies revealed that ASFV-WT and ASFV-Δ110-9L/505-7R infection led to the differential expression of TBK1 by recruiting an autophagy activator, PIK3C2B." (PMID 37162350, 2023). "Consistently, Ptk2b deficiency reduced the levels of phosphorylated STING, TBK1 and IRF3 stimulated by HSV1-GFP infection." (PMID 37989995, 2023). "Consistently, immunoblotting results showed that the levels of phosphorylated STING, TBK1 and IRF3 stimulated by HSV1-GFP infection were decreased in Ptk2b-deficient cells compared with wild-type control cells." (PMID 37989995, 2023). "Infection of NK cells with IAV resulted in the activation of TBK1, NF-κB and subsequent type-I IFN secretion." (PMID 37569596, 2023). "Our data indicated that IRF3 agonist reduced neuronal damage in the brains and spinal cords and alleviated muscle and lung pathologies, while TBK1 inhibitor exacerbated pathological changes after infection." (PMID 36626364, 2023).
infection (continued). "In this context, the cytosolic DNA sensor cyclic GMP-AMP synthase (cGAS), its downstream adaptor stimulator of interferon genes (STING) and the kinase TBK1 constitute a fundamental pathway critical for the outcome of infections." (PMID 36405710, 2022). "We first traced IFN-β expression and IFN-I signaling activation in WT mice infected with PRU tachyzoites for the indicated times and found the production of Ifnb mRNA and phosphorylation of TBK1 were enhanced at 24 h post-PRU infection." (PMID 36214572, 2022). "While total TBK1 level did not significantly change upon Ad infection, pTBK1 levels increased ~3-fold at 30 min pi and returned to basal levels within 1 h after infection, suggesting that Ad WT entry induces a fast and transient activation of TBK1." (PMID 35857795, 2022). "In contrast, much less LC3 punctae were formed upon infection in tbk1 KO cells, resulting in decreased accumulation of LC3 at Ad penetration sites." (PMID 35857795, 2022). "We repeated the infection experiment comparing WT and M1 infectivity in tbk1 KO cells versus control cells." (PMID 35857795, 2022). "In response to infection with an RNA virus, TBK1 is ubiquitinated (Ubd) on residues K69, K154, and K372; residues K69 and K154 are critical for innate antiviral responses and IFN production." (PMID 35395857, 2022). "qRT-PCR analysis showed that TBK1 was significantly silenced by shTBK1 infection when compared with shNC (p < 0.05) and the OA manifestations induced by ACLT were relieved by shTBK1." (PMID 35129065, 2022). "The analysis confirmed that total TBK1 levels remain unchanged upon infection and that TBK1 was only phosphorylated in the case of endosome penetrating WT and M1 viruses." (PMID 35857795, 2022). "Since TBK1 knockout cells were highly resistant to infection, we next wanted to evaluate the effect of a TBK1 inhibitor on leishmania infection in WT cells." (PMID 36405710, 2022). "Here we report that infection with CVB during genetic TBK1 knockdown significantly increases viral load and potentiates the bulk release of viral EVs." (PMID 36044516, 2022). "We found that the dimerization of TBK1 was lower in HDAC3fl/flLyz2-Cre peritoneal macrophage after infection with VSV." (PMID 32772249, 2021). "Accordingly, knock-down of TRAIP in primary peritoneal macrophages increased IRF3 activation upon infection with SeV, consistent with increased IFNβ production resulting from increased TBK1 activity." (PMID 33808506, 2021). "In particular, the cGAS/STING/TBK1 foreign DNA sensing pathway is a major contributor to the IFN response during infection with DNA viruses." (PMID 34903048, 2021). "The confocal images also demonstrated that knockdown of linc-AhRA attenuated the HSV-1-induced co-localization of TBK1 with TRIM27 at the late stage of infection." (PMID 34646390, 2021). "OPTN is regulated by TBK1 during infection, as inhibition of TBK1 inhibits the expression and phosphorylation of OPTN during HSV-1 infection." (PMID 34518549, 2021). "Knockdown of linc-AhRA also restored the degradation of TBK1 induced by HSV-1 infection in the late stage, echoing the previous findings that HSV-1 facilitates the degradation of TBK1 in the late stage of infection." (PMID 34646390, 2021). "With the myriad cell types HCMV infects, as well as the three different infection programs (productive, persistent, and latent), encoding multiple cGAS/STING/TBK1 pathway inhibitors likely provides flexibility and insurance." (PMID 34903048, 2021). "We found that the acetylation of TBK1 at Lys692 was strengthened and then weakened similar to Lys241, and the level of acetylation was highest at 3–5 hours post-infection with SeV." (PMID 32772249, 2021). "We also found that the acetylation of TBK1 at Lys241 was strengthened and then weakened, and the level of acetylation was highest 3 hours post-infection with SeV." (PMID 32772249, 2021).
infection (continued). "Co-immunoprecipitation of OPTN showed that upon infection OPTN first interacted with TBK1, and then with VP16." (PMID 34518549, 2021). "HDAC3-mediated deacetylation of TBK1 at Lys241 and Lys692 occurred during the late stage after SeV challenge (5 hours post-infection)." (PMID 32772249, 2021). "Human MDMs were incubated with IFNAR and IFNLR neutralizing antibodies or the TBK1/IKKε inhibitor BX795 (as a control) prior to infection with HMPV." (PMID 34248923, 2021). "Our work adds to the list of HCMV factors that inactivate the cGAS/STING/TBK1 pathway during productive infections of highly differentiated cells and initiates the list of those that do so during latency within incompletely differentiated myeloid cells." (PMID 34903048, 2021). "TBK1 k.o. cells have a ~10-fold lower IFN-β induction upon infection with EMCV-LZn, transfection of vRNA or upon overexpression of MAVS." (PMID 32667958, 2020). "TBK1 in the cytoplasmic fraction was slightly but significantly upregulated at 12 (p < 0.01), 18 (p < 0.01), and 24 (p < 0.001) h post infection." (PMID 32922394, 2020). "NK92 cell infection induced TBK1 expression, mainly after HHV-6A infection (p = 0.011; Student t test)." (PMID 32140147, 2020). "Post-infection 24 and 48 h, p-TBK1 was observably increased, whereas it was decreased in the siRNA group." (PMID 30791397, 2019). "The detection of upregulated Toll, IMD, STAT, and TBK1 gene expressions in P. monodon hepatopancreas during AHPND infection in the present study indicates the activation of corresponding TLRs, IMD, JAK-STAT, and cytosolic sensing pathways." (PMID 31372182, 2019). "TBK1 subsequently phosphorylates the selective autophagy receptor p62, which leads to the induction of autophagy upon infection with several different DNA and RNA viruses." (PMID 32039206, 2019). "The K63-linked ubiquitination of STING mediated by TRIM56 and TRIM32 promotes TBK1–STING interaction upon infection with Sendai virus (SeV) or HSV-1." (PMID 29760876, 2018). "As expected, cells deficient in Tbk1 or Irf3 appeared to have weaker levels of Tbk1 or Irf3 phosphorylation, respectively, indicating other pathways involved in Tbk1 or Irf3 were activated during the ECTV infection." (PMID 29963044, 2018). "Inducible expressions of TBK1 and TBK1_tv1 were analyzed in vitro after SVCV infection using anti-TBK1 antibody." (PMID 29441066, 2018). "For the host, activation of TBK1 and IKKi in response to pathogen infection is vital for initiating the antiviral response." (PMID 29441066, 2018). "TANK-binding kinase 1 (TBK1) is involved in innate immunity, prompting transcriptional induction of type I interferons in response to pathogenic infection." (PMID 30662438, 2018). "Overall, these data suggest that zebrafish TBK1_tv1 and TBK1_tv2 associate with TBK1 and IRF3 to disrupt TBK1-IRF3 interaction under physiological conditions and SVCV infection." (PMID 29441066, 2018). "We examined the effect of TBK1 signaling on the expression of cell surface molecules in DCs upon infection with ΔN146." (PMID 28150813, 2017). "Upon infection, the TRAFs-TBK1/IKKε complex was recruited to MAVS, likely bringing TBK1/IKKε close enough to cause the trans-autophosphorylation." (PMID 29125880, 2017). "As expected, viral protein levels were higher in Tbk1-/- cells than in Tbk1+/+ cells, as Tbk1 knockout cells are more permissive to infection." (PMID 28953980, 2017). "As the pivotal role of TBK1 in various immunobiological and immunopathological events, its activity must be tightly regulated to effectively control pathogen infection and maintain immune homeostasis." (PMID 28714877, 2017). "We found p-TBK-1 increased markedly and the whole TBK-1 decreased with siAIM2-targeting of transfected BMDMs after infection with M. bovis." (PMID 27409673, 2016).